PNLIPRP2 (pancreatic lipase related protein 2 (gene/pseudogene))
Description:
Lipase that primarily hydrolyzes triglycerides and galactosylglycerides. In neonates, may play a major role in pancreatic digestion of dietary fats such as milk fat globules enriched in long-chain triglycerides. Hydrolyzes short-, medium- and long-chain fatty acyls in triglycerides without apparent positional specificity. Can completely deacylate triacylglycerols. When the liver matures and bile salt synthesis increases, likely functions mainly as a galactolipase and monoacylglycerol lipase. Hydrolyzes monogalactosyldiglycerols (MGDG) and digalactosyldiacylglycerols (DGDG) present in a plant-based diet, releasing long-chain polyunsaturated fatty acids. Hydrolyzes medium- and long-chain fatty acyls in galactolipids. May act together with LIPF to hydrolyze partially digested triglycerides. Hydrolyzes long-chain monoglycerides with high efficiency. In cytotoxic T cells, contributes to perforin-dependent cell lysis, but is unlikely to mediate direct cytotoxicity (By similarity). Also has low phospholipase activity. In neurons, required for the localization of the phospholipid 1-oleoyl-2-palmitoyl-PC (OPPC) to neurite tips through acyl chain remodeling of membrane phospholipids (By similarity). The resulting OPPC-rich lipid membrane domain recruits the t-SNARE protein STX4 by selectively interacting with the STX4 transmembrane domain and this promotes surface expression of the dopamine transporter SLC6A3/DAT at neurite tips by facilitating fusion of SLC6A3-containing transport vesicles with the plasma membrane (By similarity).
Synonyms: PLRP2
Target class: Enzyme; Hydrolase
Gene: Protein-coding gene on chromosome 10 (116,620,953 to 116,645,143, forward strand). Ensembl gene ENSG00000266200.
Subcellular location: Secreted; Zymogen granule membrane; Cell projection, neuron projection
Pathways (Reactome):
Developmental Biology: Developmental Lineage of Pancreatic Acinar Cells
Digestion and absorption: Digestion of dietary lipid
Genetic constraint (gnomAD): Loss-of-function variants: 27 observed, 29.55 expected, observed/expected ratio (o/e) 0.91, 90% interval 0.67 to 1.26. The upper end of that interval is the gene's LOEUF score, 1.26, which puts it in group 5 of 6, group 1 being the genes least tolerant of losing a copy. Missense variants: 376 observed, 357.54 expected, observed/expected ratio (o/e) 1.05, 90% interval 0.97 to 1.14. Synonymous variants: 157 observed, 142.53 expected, observed/expected ratio (o/e) 1.1, 90% interval 0.97 to 1.26.
Homologues: Orthologues: chimpanzee PNLIPRP2 (98% identical), macaque PNLIPRP2 (91% identical), pig PNLIPRP2 (77% identical), mouse Pnliprp2 (75% identical), rat Pnliprp2 (75% identical), rabbit PNLIPRP2 (73% identical), guinea pig PNLIPRP2 (70% identical), tropical clawed frog pnliprp2 (57% identical), tropical clawed frog pnliprp2 (51% identical), tropical clawed frog pnliprp1 (49% identical), tropical clawed frog pnliprp3 (46% identical), Drosophila melanogaster CG18258 (22% identical), and 14 more. Paralogues in human: PNLIP (63% identical), PNLIPRP1 (62% identical), PNLIPRP3 (47% identical), LIPC (29% identical), LIPG (29% identical), LIPH (28% identical), LIPI (28% identical), LPL (27% identical), PLA1A (25% identical).
Diseases named in the same sentence as PNLIPRP2 in open-access papers:
PNLIPRP2 is named in the same sentence as 12 diseases in open-access papers, as found by Europe PMC text mining. Sharing a sentence is not in itself a finding about the gene and the disease. The quoted sentences say what the papers report.
chronic pancreatitis (1 paper, 2018). A chronic inflammatory process causing damage and fibrosis of the pancreatic parenchyma. "Genotype distribution of PNLIPRP2 variants in patients with chronic pancreatitis (CP) and in controls." (PMID 30408063, 2018). "Distribution of common PNLIPRP2 haplotype alleles in patients with chronic pancreatitis (CP) and in controls." (PMID 30408063, 2018). "We sequenced exon 11 of PNLIPRP2 in a cohort of 256 subjects with chronic pancreatitis (152 alcoholic and 104 non-alcoholic) and 200 controls of Hungarian origin." (PMID 30408063, 2018). "Allele frequency of PNLIPRP2 variants in patients with chronic pancreatitis (CP) and controls without pancreatic disease." (PMID 30408063, 2018).
diabetes (1 paper, 2005). "By facilitating fat storage, the consequence of which is hyperglycemic diabetes, the selective decrease in Pnliprp2 in TH mice may explain Tanidd1, and potentially, the genetically overlapping T2dm2 QTL." (PMID 15760467, 2005).
Insulin resistance (1 paper, 2022). Increased resistance towards insulin, that is, diminished effectiveness of insulin in reducing blood glucose levels. "Regardless of insulin resistance, the two groups of women with morbid obesity showed upregulation of LYPD8 and downregulation of a greater number of genes, such as REG1B, GKN2, LPL, PNLIPRP2, FKBP5, and CD86, that are related to responses to bacterial stimuli and antimicrobial activity." (PMID 35625760, 2022).
pancreatic disease (1 paper, 2018). "Allele frequency of PNLIPRP2 variants in patients with alcoholic chronic pancreatitis (ACP) and controls without pancreatic disease." (PMID 30408063, 2018). "Allele frequency of PNLIPRP2 variants in patients with non-alcoholic chronic pancreatitis (NACP) and controls without pancreatic disease." (PMID 30408063, 2018).
cancer (1 paper, 2022). A tumor composed of atypical neoplastic, often pleomorphic cells that invade other tissues. "Three pseudogenes (RPL26P29, PNLIPRP2, and CSAG4) are included in the top three miRNA–RNA pairs with the smallest p-value, and several miRNA-pseudogene pairs were found as potential prognostic pairs for all 7 types of cancer." (PMID 35430805, 2022).
tumor (1 paper, 2018). "Exocrine like- Increased expression of tumor cell-derived digestive enzyme genes, e.g. Islet-derived 1 beta (REG1B), pancreatic lipase-related protein 2 (PNLIPRP2), and cystic fibrosis transmembrane conductance regulator (CFTR)." (PMID 29928492, 2018).
PNLIPRP2 also shares sentences with these, for which no sentence is quoted: pancreatitis (2 papers); acute pancreatitis (1); heart failure (1); malaria (1); morbid obesity (1); Obesity (1).